EPCAM (epithelial cell adhesion molecule)
Diseases named in the same sentence as EPCAM in open-access papers (continued):
Sharing a sentence is not in itself a finding about the gene and the disease.
breast carcinoma (continued). "In the current study, the CTC detection methods CytoTrackTM and CellSearch are compared with an in vitro assessment using spiking experiments with the breast cancer cell line MCF-7 positive for both epithelial cell adhesion molecule (EpCAM) and pancytokeratin." (PMID 25608842, 2015). "Overexpression of EpCAM in breast cancer cells enhanced tumor cell growth in vitro and increased invasiveness, whereas small interfering RNA-mediated silencing of EpCAM (si-EpCAM) had the opposite effect." (PMID 26356670, 2015). "Circulating tumor cells shed from breast carcinoma, are a heterogeneous population including EpCAM-positive cells and cells with mesenchymal phenotype (EMT), which are studied for the analysis of the therapeutic response to different chemotherapeutic regimens." (PMID 26703564, 2015). "EpCAM expression based assay is the only FDA-approved test widely used to detect circulating tumor cells in breast cancer." (PMID 25695234, 2015). "In this study, we evaluated the effect of changes in EpCAM expression levels on the growth and metastasis of breast cancer cells in vitro and in vivo through RNA interference or overexpression method." (PMID 26356670, 2015). "In patients with node-positive primary breast cancer, elevated EpCAM expression correlates with diminished overall survival, suggesting that overexpression of EpCAM promotes cancer progression and metastasis." (PMID 25885919, 2015). "In 2013, Baccelli studied metastasis of circulating tumor cells in the blood of breast cancer patients and reported that metastasis-initiating cells had an EPCAM+CD44+CD47+c-met+ phenotype." (PMID 25658794, 2015). "Our in vitro assay indicated that the ability of EpCAM to promote metastasis is mainly due to its effect on the regulation of breast cancer cell migration and invasion." (PMID 26356670, 2015). "The aim of this paper was to evaluate the ability of multi-marker IE/FACS based on immunomagnetic separation with EpCAM to recover spiked cancer cells across the spectrum of intrinsic subtypes in breast cancer." (PMID 26556851, 2015). "Consistent with their report, our study indicated that the upregulation and activation of MMP-9 via the Ras/Raf/ERK signaling pathway was required for EpCAM-mediated growth and invasion of breast cancer cells." (PMID 26356670, 2015). "In benign cancer breast tissue, epithelial cells in the lumen express low levels of the epithelial marker EPCAM, but in different tumour tissues, including breast cancer, cell adhesion molecules are overexpressed." (PMID 25978366, 2015). "In 2013, Baccelli studied the metastasis of circulating tumor cells in the blood of breast cancer patients and reported that metastasis-initiating cells had an EPCAM+CD44+CD47+c-met+ phenotype." (PMID 25658794, 2015). "Together, our current observations point to a potential oncogenic role for EpCAM in breast cancer cell invasion and migration, possibly via activation of the Ras/Raf/EFK pathway by MMP-9 upregulation through Fos and Jun." (PMID 26356670, 2015). "In this study, we found that EpCAM expression was increased in tumor tissue from breast cancer patients compared to healthy patients." (PMID 26356670, 2015). "In conclusion, our data show that knockdown of EpCAM can inhibition breast cancer cell growth and metastasis via inhibition of the Ras/Raf/ERK signaling pathway and MMP-9." (PMID 26356670, 2015). "In a second step, EpCAM-depleted supernatants comprising potential CTCs that had escaped EpCAM-based selection were used to evaluate our markers in metastatic breast cancer samples." (PMID 26695635, 2015). "We detected the presence of neoplastic and breast cancer stem cell markers coupled with negativity for EpCAM." (PMID 26631983, 2015). "Taken together, it appears that EpCAM promotes breast cancer growth and invasion through regulation of MMP-9 expression." (PMID 26356670, 2015).
breast carcinoma (continued). "After the surface amination, the nanoparticles were further bioconjugated with breast cancer-specific monoclonal antibody (anti-EpCAM) to form ZGG-EpCAM nanoprobes which can specifically target breast cancer cell lines (MCF7) in vitro." (PMID 30464964, 2015). "In the present study, we identified EpCAM as a candidate target gene for the inhibition of breast cancer growth and metastasis." (PMID 26356670, 2015). "We also performed in vivo studies using xenograft model in nude mice with MCF7 breast cancer cell line, as a proof of concept for solid epithelial cancers which expresses EpCAM." (PMID 26176230, 2015). "To further confirm this relationship, we analyzed EpCAM expression in normal human breast and breast cancer tissue by immunohistochemistry." (PMID 26356670, 2015). "In our study, we found that knockdown of EpCAM in breast cancer cells significantly decreased the expression of Ras, pRaf, and pERK." (PMID 26356670, 2015). "The current study demonstrated that our EpCAM based IE/FACS CTC isolation strategy can efficiently capture most breast cancer subtypes." (PMID 26556851, 2015). "In this context, a recent study in 1365 breast cancers reported EpCAM expression varies significantly and is differentially associated with prognosis in the luminal B HER2 positive, basal like, and HER2 intrinsic subtypes of breast cancer." (PMID 25265904, 2014). "This association between EpCAM and ERAP2 suggests a new mechanism of EpCAM processing and regulation of antigen presentation in breast cancer." (PMID 25265904, 2014). "Our results showed that knockdown of EpCAM enhances the chemosensitivity of breast cancer cells to 5-FU by downregulating the expression of Bcl-2, suggesting EpCAM as a promising target for anti-cancer therapy." (PMID 25019346, 2014). "One of its uses is for on-filter IHC analysis of HER2 and ER/PgR protein expression and FISH analysis of HER2 gene amplification in breast cancer cases, in addition to routine EpCAM and CD45 staining." (PMID 24523941, 2014). "Metastatic breast cancer patients have atypical cells that are CK + EpCAM − circulating in their blood." (PMID 24602188, 2014). "Herein, we examined the expression of nuclear and cytoplasmic Ep-ICD, and membranous extracellular domain of EpCAM (EpEx) in breast cancer patients, to determine its potential utility in predicting aggressive clinical course of the disease." (PMID 25265904, 2014). "EpCAM expression has been used to predict response to anti-EpCAM antibodies in breast cancer patients." (PMID 25265904, 2014). "Expression of Cell Surface Markers and Aldefluoractivity in EpCAM Positive Cells from Two Breast Cancer Xenografts Models, measured by flow cytometry." (PMID 25419568, 2014). "EpCAM is overexpressed in many cancers including breast cancer and EpCAM overexpression is correlated with decreased survival of patients, making it an attractive diagnostic and therapeutic target in oncology." (PMID 25019346, 2014). "In the present study, we investigated the effect of EpCAM on the chemosensitivity of breast cancer cells." (PMID 25019346, 2014). "Epithelial cell adhesion molecule (EpCAM) is a membrane glycoprotein that is expressed in a subset of normal epithelia and is highly expressed on most carcinomas, including breast cancer." (PMID 25019346, 2014). "Fresh tumor material from five randomly chosen breast cancer patients was disaggregated and triple stained with anti-EpCAM, anti-CD24 and anti-SSEA-4 antibodies." (PMID 25419568, 2014). "From a group of 17 breast cancer patients, single tumor cells were collected using anti-EpCAM microbeads and the MagSweeper from 30 blood samples, a bone marrow biopsy, and six fresh tumor tissues." (PMID 24947048, 2014). "Mostert and coworkers undertook a clinical study in primary breast cancer patients in which both EpCAM and CD146-positive circulating tumor cells (CTCs) were studied to establish the clinical relevance of cell lines including the SUM cell lines." (PMID 23401782, 2013).
breast carcinoma (continued). "The intensity of antibody staining for the three different breast cancer xenografts using an anti-EpCAM antibody 323/A3 was much weaker than that of the aptamers, in particular aptamer Ep23." (PMID 23460885, 2013). "This background will allow us to understand the impact of EpCAM overexpression on transformation of breast epithelial cells and growth of breast cancer cells." (PMID 23758908, 2013). "The Epithelial Cell Adhesion Molecule (EpCAM) has been shown to be strongly expressed in human breast cancer and cancer stem cells and its overexpression has been supposed to support tumor progression and metastasis." (PMID 23758908, 2013). "To confirm the sensitivity of our aptamers, we initially chose several breast cancer cell lines that have a known level of EpCAM expression on their cell surface, as well as a colon cancer cell line that has a known high level of EpCAM expression." (PMID 23460885, 2013). "We also found a direct ZEB1-mediated repression of EPCAM in human pancreatic and breast cancer cell lines, indicating a conserved regulatory circuit." (PMID 23667256, 2013). "EpCAM is a cancer biomarker with its overexpression documented in both primary and metastatic breast cancers." (PMID 23460885, 2013). "In breast carcinoma patients, high EpCAM expression was observed in less differentiated tumors and was associated with larger tumors, nodal metastasis and worse survival of patients." (PMID 23758908, 2013). "Mostert and colleagues set out to identify an additional new marker to be used after capturing breast cancer cells with combined anti-CD146/anti-EpCAM, to detect those cancer cells that lack CK8/18/19 expression." (PMID 23401782, 2013). "Despite the prognostic impact of CTC counts in breast cancer, mainly using EpCAM-based capturing methods, it has been shown that this procedure is not able to detect the entire, highly heterogenous population of CTC." (PMID 22264265, 2012). "EpCAM gene and protein expression was analyzed in various breast cancer cell lines, immortalized (MCF-10A) and normal mammary epithelial cells (HMECs)." (PMID 23110550, 2012). "EpCAM is overexpressed 100- to 1000-fold in primary and metastatic breast cancer relative to normal breast cells." (PMID 22646670, 2012). "They found that overexpression of EpCAM in vivo inhibited the invasive growth of fibroblastic L cells and dedifferentiated mammary carcinoma L153S cells." (PMID 23110550, 2012). "The epithelial cell adhesion molecule (EpCAM) has been shown to be overexpressed in breast cancer and stem cells and has emerged as an attractive target for immunotherapy of breast cancer patients." (PMID 23110550, 2012). "This study analyzed different types of breast carcinoma cells derived from metastasis for their expression of EpCAM." (PMID 23110550, 2012). "In human breast cancer patients, the EpCAM-specific antibody adecatumumab shows EpCAM-dependent activity in clinical studies." (PMID 23110550, 2012). "For this purpose, shRNA-mediated knockdown of EpCAM gene expression was performed in EpCAMhigh breast cancer cell lines with epithelial phenotype (MCF-7, T47D and SkBR3)." (PMID 23110550, 2012). "Down-regulation of EpCAM has been reported independently for DTCs in bone marrow and CTCs in peripheral blood of patients with breast cancer and for other solid tumors." (PMID 22591372, 2012). "It has previously been reported that human breast cancer stem cells often have an EpCAM+CD44+CD24-/low phenotype." (PMID 23088371, 2012). "This study analyzes the effects of EpCAM on breast cancer cell lines with epithelial or mesenchymal phenotype." (PMID 23110550, 2012). "The role of EpCAM in breast cancer changes with tumor cell phenotype and the respective tumor microenvironment." (PMID 23110550, 2012). "The role of EpCAM in breast cancer strongly depends on the epithelial or mesenchymal phenotype of tumor cells." (PMID 23110550, 2012).
breast carcinoma (continued). "Representative data from our S2N and S2 cell lines also challenge the validity of the CD24−/CD44+ marker combination and EpCAM expression as tumorigenicity markers in breast cancer." (PMID 23042145, 2012). "We also demonstrate that the sensitivity of the assay was significantly dependent on the expression levels of EpCAM, which was causally linked to its failure to detect any positive CTC sample in murine breast cancer xenograft models." (PMID 22591372, 2012). "Particularly, in breast carcinoma cells with high cytokeratin-18 and E-cadherin expression, i.e. epithelial phenotype, EpCAM displays growth- and invasion-promoting effects." (PMID 23110550, 2012). "Our data are in line with reports on pharyngeal, lung and breast cancer cells, where EpCAM seems to support tumor progression." (PMID 23110550, 2012). "Addition of rEpCAM to MDA-231 breast cancer cells is able to rescue invasion following specific ablation of EpCAM." (PMID 22132731, 2011). "Constitutively active JNK MAPK constructs rescued c-Jun phosphorylation and AP-1 transcription factor activity following specific ablation of EpCAM in MCF-7 breast cancer cells." (PMID 22132731, 2011). "In order to investigate changes of the transcriptome on EpCAM gene overexpression in human breast cancer cells, global gene expression analysis using the human genome U133 Plus 2.0 chip (Affymetrix) was performed." (PMID 21281469, 2011). "Basal-like breast cancer, which is associated with mutations in the tumor suppressor gene BRCA1, appears to be more closely related to an EpCAM+ luminal-restricted progenitor cell population." (PMID 21952072, 2011). "We have previously reported that specific ablation of EpCAM decreases breast cancer invasion in vitro." (PMID 22132731, 2011). "In these experiments, EpCAM rescue in MDA-231 and CA1a breast cancer cells results in EpCAM overexpression as measured by immunoblot, and increased invasion, establishing a gain-of-function model system." (PMID 22132731, 2011). "Functional studies confirm that AP-1 is a key downstream mediator of EpCAM biology, contributing to EpCAM-dependent breast cancer invasion." (PMID 22132731, 2011). "EpCAM thus appear to be a more universal marker of breast cancer micrometastasis than pure epithelial derived targets, as it will also detect tumor cells with EMT-like characteristics." (PMID 21816090, 2011). "In a recent study, EpCAM was shown to be over-expressed on all breast cancer metastases relative to the matched primary tumor." (PMID 21816090, 2011). "In functional rescue experiments, forced expression of c-Jun rescues invasion in breast cancer cells following specific ablation of EpCAM." (PMID 22132731, 2011). "Using SDS-PAGE, EpCAM protein was detectable as a double band in both transfected breast cancer cell lines as well as in MCF-7 control lines under denaturing conditions." (PMID 21281469, 2011). "Stable specific ablation of EpCAM in both MDA-231 and CA1a breast cancer cell lines is also associated with a more than 80% decrease in invasion in matrigel transwell invasion assays." (PMID 22132731, 2011). "Stable transduction of breast cancer cell lines with EpCAM-specific lentiviral shRNA constructs results in more than 90% reduction in EpCAM protein expression as measured by immunoblot." (PMID 22132731, 2011). "For example, in breast cancer, high EpCAM expression correlates with poor prognosis, and downregulation of EpCAM has been shown to decrease the oncogenic potential." (PMID 21694727, 2011). "Specific ablation of EpCAM expression in MDA-231 breast cancer cells significantly decreases tumor growth following tumor challenge in nude mice." (PMID 22132731, 2011). "Recent genome-wide analysis suggests that this newly discovered intrinsic subtype of breast cancer is closely related to putative EpCAM- mammary stem cells." (PMID 21952072, 2011).
breast carcinoma (continued). "To confirm and extend these findings, we specifically ablated EpCAM in breast cancer cells (CA1a, and MCF-7), and then measured the levels of total and phosphorylated c-Jun by protein immunoblot and densitometry." (PMID 22132731, 2011). "In breast cancer, the EpCAM antigen is overexpressed in 30-40% of all cases and this increased expression correlates with poor prognosis." (PMID 21281469, 2011). "In this retrospective analysis the patient subgroup with breast carcinomas overexpressing both EpCAM and Her-2/neu had the worst prognosis." (PMID 21281469, 2011). "In order to explore molecular changes following EpCAM overexpression, we investigated changes of the transcriptome upon EpCAM gene expression in commercially available human breast cancer cells lines Hs578T and MDA-MB-231." (PMID 21281469, 2011). "EpCAM is a cell-surface glycoprotein that is overexpressed on the majority of epithelial cancers, including breast cancer." (PMID 22132731, 2011). "EpCAM expression was manipulated in breast cancer cell lines using RNA interference and cDNA expression constructs." (PMID 22132731, 2011). "We used the lentiviral vectors validated above to determine the impact of EpCAM expression on breast cancer invasion in vivo, taking advantage of a commonly used breast cancer xenograft model." (PMID 22132731, 2011). "In this small study, we surprisingly found that the majority of human breast cancer tissues exhibited a EpCAM+/CD49f+ luminal epithelial differentiation phenotype regardless of their molecular subtype." (PMID 20964822, 2010). "Breast cancer cell line MCF-7 has been identified by knockdown experiments as being dependent on EpCAM for proliferation, which is why it was here selected for further characterization of antibodies." (PMID 21044305, 2010). "In reduction mammoplasty tissues, EpCAM+/CD24-/CD49f+ cells exhibited a basal cytokeratin phenotype while breast cancer cell lines with a basal-like phenotype also contained a unique population of EpCAM+/CD24-/CD49f+ cells." (PMID 20964822, 2010). "In the blood of breast cancer patients, we found EpCAM over-expression in 5.0% of the patients at primary diagnosis and in 19.4% of the patients with clinical evidence of disease recurrence." (PMID 21129172, 2010). "Several authors reported the heterogeneous expression of EpCAM in mammary carcinomas and downregulation of EpCAM has been reported for disseminated tumour cells in bone marrow and CTCs in peripheral blood." (PMID 19953098, 2010). "Blood of 431 patients with primary breast cancer were analyzed for EpCAM, MUC1 and HER2 transcripts with the AdnaTest BreastCancerTM (AdnaGen AG, Germany)." (PMID 19664291, 2009). "Here we also compared the CTC enrichment and detection using anti-CK alone and the combination of anti-CK and anti-EpCAM antibodies in blood samples from breast cancer patients." (PMID 18687126, 2008). "Several authors reported the heterogeneous expression of EpCAM in mammary carcinomas; downregulation of EpCAM was reported for disseminated tumor cells in bone marrow and CTCs in peripheral blood." (PMID 18687126, 2008). "The interacting protein CD44 and EpCAM were part of the CSC signature in not only breast cancer but also colon." (PMID 18852874, 2008). "For this study we selected seven breast cancer-associated genes [mam, CEA, CK19, PIP, muc1, PSE, Erb (BM only) and EpCAM (PBL only)] known to be over-expressed in metastatic breast cancer compared to control lymph nodes." (PMID 18289390, 2008). "The anti-CK antibody-based CTC-enrichment method uses an intracellular CK protein marker to enrich CTCs and achieve better sensitivity of CTC detection than that of the surface EpCAM protein marker in blood samples from breast cancer patients." (PMID 18687126, 2008). "On the other hand, knockdown of EpCAM by EpCAM short-interfering RNA resulted in a decrease in the cell proliferation rate in four different breast cancer cell lines." (PMID 19002182, 2008).